KLF3 (KLF transcription factor 3)
Diseases named in the same sentence as KLF3 in open-access papers (continued):
Sharing a sentence is not in itself a finding about the gene and the disease.
cardiovascular disorder (1 paper, 2013). A disease involving the cardiovascular system. "The discoveries reported here provide impetus for exploring the KLF3 pathway to discover new causative factors contributing to cardiovascular disorders in humans." (PMID 23874215, 2013). "Future exploration of the KLF3 pathway provides a new avenue for investigating causative factors contributing to cardiovascular disorders in humans." (PMID 23874215, 2013).
KLF3 also shares sentences with these, for which no sentence is quoted: prostate carcinoma (3 papers); acute myelocytic leukemia (2); gastric cancer (2); glioma (2); neurological disorders (2); renal carcinoma (2); stomach cancer (2); acute leukemia (1); atherosclerosis (1); carcinoid (1); cardiac hypertrophy (1); endometrial tumors (1); endometrioid endometrial carcinoma (1); Fat (1); Glucose intolerance (1); head and neck cancer (1); hepatocellular carcinoma (1); infection (1); invasive breast carcinoma (1); metastatic disease (1); Pan (1); pancreatic neuroendocrine tumor (1); renal fibrosis (1); retinitis pigmentosa (1); skin cancer (1); T-cell leukemia (1); thyroid cancer (1); viral infection (1).